TERT (telomerase reverse transcriptase)
Diseases named in the same sentence as TERT in open-access papers (continued):
Sharing a sentence is not in itself a finding about the gene and the disease.
cancer (continued). "Comparison of TERT- positive and negative cancers showed the differential activation of 496 genes and 1975 molecular pathways." (PMID 38859942, 2024). "In many cancers, inhibiting MAPK pathway effectors inhibits TERT mRNA expression." (PMID 38278800, 2024). "TERT and TERC are accompanied by auxiliary proteins that are necessary for telomere homeostasis, which is essential in the regulation of aging and cancer formation, such as the structure-stabilizing proteins called dyskerin (DKC1) and non-histone chromosome protein 2 (NHP2)." (PMID 38671875, 2024). "We observed a bimodal distribution of TERT expression where ∼27% of cancer samples did not express TERT and the rest showed a bell-shaped distribution." (PMID 38859942, 2024). "Together, these data establish a non-canonical role for TERT in promoting clonal competition in stem cells in vivo, with implications for understanding tissue homeostasis, cancer development and telomere maintenance." (PMID 39020172, 2024). "Plk1 interacts directly with TERT, independently of its kinase activity, and enhances the stability of TERT by inhibiting its ubiquitin-mediated degradation by MKRN1 and HDM2, thereby increasing cancer cell telomerase activity." (PMID 38278800, 2024). "We add support to the non-canonical function of TERT expression related to mitochondrial and nuclear DNA stability even across cancer entities, especially under hypoxic conditions and after chromothripsis." (PMID 37418389, 2023). "Due to their low expression levels (∼1000 molecules per cell in cancer cells), both TERT and TR are not straightforward to study." (PMID 38108475, 2023). "Thus, it would be highly interesting to explore the cellular localization of TERT and DNA2 in various cancers and in the context of hypoxia." (PMID 37418389, 2023). "Next, we determined that TERT AS is impacted by cell density in stem cells (iPSCs) but not in cancer cells (Calu-6)." (PMID 37531400, 2023). "It was discovered that TERT interacts with RNA other than TERC (e.g. RNA component of mitochondrial RNA processing endoribonuclease [RMRP]) and subsequently serves as an RNA polymerase to produce double‐stranded RNAs in cancer cell lines (HeLa, 293T and MCF7)." (PMID 37041671, 2023). "Telomerase reverse transcriptase (TERT), in addition to potentiating cancer stemness, metastasis, and telomere length maintenance, also promotes anchorage-independent growth of cancer cells." (PMID 37384249, 2023). "We also found that splice-switching of TERT, which regulates telomerase activity, is induced by different cell densities in stem cells but not cancer cells." (PMID 37531400, 2023). "Our data revealed that certain SFs are dysregulated in cancer and do not seem to play a role in TERT regulation in stem cells." (PMID 37531400, 2023). "TERT expression positively correlated with infiltration of B and T cells (adaptive immune cells) in non-TNBC, BLCA, SKCM, and LIHC cancers, with the strongest association in HNSCC (FDR < 0.05)." (PMID 36909826, 2023). "We thus performed immune-morphological studies with cancer-related markers such as α-methylacyl-CoA racemase (AMACR), prostate-specific membrane antigen (PSMA), and telomerase reverse transcriptase (TERT) to understand if the giant cells we found are PGCC or other urinary cells." (PMID 37444476, 2023). "However, the ability of the TERT gene to encode a regulatable enzyme that controls the telomerase expression and telomere lengthening through inserting repetitive nucleotide units (5′-TTAGGG-3′) at the chromosomal terminus could determine the proliferation level of carcinoma 18,24." (PMID 37884663, 2023). "TERT is expressed at low levels or not detectable in normal somatic cells and tissues while its expression is upregulated in most carcinoma cells and highly proliferative organs." (PMID 36938425, 2023). "Many other cancers express TERT mRNA by less clearly defined means that do not involve TERT genetic alterations (i.e., wild-type cancers)." (PMID 36011010, 2022).
cancer (continued). "Methylation of the TERT hypermethylated oncological region (THOR), a 433-base pair (bp) sequence upstream of the canonical TERT core promoter, is a frequent gain-of-function mechanism found in cancer." (PMID 35406427, 2022). "This TERT SNP has been identified in a range of other cancers and may act to disrupt a pre-existing ETS binding site in the TERT promoter." (PMID 35494035, 2022). "For example, ectopic expression of TERT in fibroblasts leads to reactivation of telomerase activity (which is absent in normal fibroblasts), and silencing of TERT in cancer cells leads to inhibition of telomerase activity." (PMID 36499514, 2022). "Although most somatic cells do not express TERT in humans, TERT mRNA is shuttled from cancer cells via exosomes and turns nonmalignant telomerase negative cells into telomerase positive cells." (PMID 35741087, 2022). "TERT promoter methylation is enriched in cancers lacking TERT genetic alterations (wild-type cancers), but its functional impact on TERT transcription remains elusive." (PMID 36011010, 2022). "We performed meta-analyses to assess correlations between 23 variants within TERT-CLPTM1L region and susceptibility to 12 cancers and 1 non-cancer disease based on data in 109 papers (involving 139,510 cases and 208,530 controls)." (PMID 35847915, 2022). "Moreover, FOS inhibitors were recently observed to induce robust apoptosis in cancer cells harboring a mutant TERT promoter by suppressing GABPB1 and TERT expression." (PMID 35326537, 2022). "From the studies, we can conclude that TERT plays a noncanonical role that regulates cancer development through different mechanisms from telomere regulation in the nucleus." (PMID 35741087, 2022). "Beside its well-established role in telomere synthesis, several studies demonstrated that TERT possesses non-canonical activities that foster cancer cell proliferation and adult stem/progenitor cells activation." (PMID 35149726, 2022). "Although TERT promoter hypermethylation is enriched in wild-type cancers, it is not mutually exclusive to TERT activating genetic alterations, as predicted for functionally redundant mechanisms." (PMID 36011010, 2022). "Interestingly, in small sets of patients with HCC, AAV showed insertional oncogenic mutagenesis similar to HBV, with a common hot spot of viral insertion within TERT, CCNE1, and CCNA2 cancer driver genes, leading to their overexpression." (PMID 36316711, 2022). "Epidemiological evidence for associations between variants in the TERT and CLPTM1L gene with risk of cancer and non-cancerous diseases in additive model." (PMID 35847915, 2022). "TERT is normally silenced in nontumor cells but is reactivated via regulatory mechanisms that maintain the telomere length in human cancer cells, allowing them to survive." (PMID 35884575, 2022). "Our laboratory established for the first time that downstream MAP kinase signalling, ETS transcription factors bind to the TERT gene promoter ETS binding motif (CCTT) directly, functioning as an essentially key transcription factor for TERT gene expression in cancer." (PMID 35269498, 2022). "In our study, available data from 109 papers were extracted in these meta-analyses, thus further evaluating associations between 23 variants in TERT-CLPTM1L region and 12 cancers and 1 non-cancer disease under an additive genetic model." (PMID 35847915, 2022). "Even patients with cancers overexpressing telomerase are unlikely to be jeopardized by TERT reactivation in benign cells, although they are possibly an increased risk group." (PMID 36552277, 2022). "This regulation does not require the presence of TERC, suggesting that TERT–MYC interaction on MYC-regulated promoters are independent of telomerase activity and could also explain why TERT and MYC levels are highly correlated in cancer cells." (PMID 33599797, 2021).
cancer (continued). "Specifically, these TERT-negative cancer types were related to adrenal, kidney, thyroid, brain or soft tissue origin." (PMID 33924498, 2021). "The results throw light on the noncanonical role of TERT in promoting cancer invasiveness and reveal novel targets for therapeutic intervention." (PMID 33713376, 2021). "This is a novel noncanonical telomerase function, since it is independent of telomerase activity, thus paving the way towards the development of new therapeutic strategies to fight cancer through the inhibition of noncanonical activities of TERT." (PMID 33713376, 2021). "Researchers are now paying more attention to the regulation of telomerase or TERT because of their unique characteristic of low or no expression in normal somatic cells, but high expression in cancer cells." (PMID 34395278, 2021). "TERT is found not only in the nucleus but also in the cytoplasm and mitochondria and is involved in tumorigenesis and cancer therapy resistance independent of telomere lengthening." (PMID 34439356, 2021). "Thus, the HCV-core-induced miR-138 inhibition was considered as one of the mechanisms able to reactivate TERT expression in HCV-infected cells, possibly leading to cancer development." (PMID 34069740, 2021). "Increasing evidence points to the noncanonical roles of TERT, not only in cancer but also in several essential cellular functions, via mechanisms that are independent of telomere maintenance." (PMID 33713376, 2021). "This is fundamental in deepening our understanding of the telomeric vs. non-telomeric functions of TERT in cancer development and other diseases." (PMID 33599797, 2021). "Increased TERT mRNA levels were observed after overexpression of SMYD3, while its suppression led to reduced H3K4 trimethylation within the TERT core promoter and also decreased the ability of MYC and SP1 to bind the promoter in cancer cell lines." (PMID 33802026, 2021). "The mechanism(s) by which high TERT expression ultimately facilitates cancer progression and constitutes a prognostic factor are not completely elucidated, and seems not be attributable only to TERT’s ability to maintain telomere length." (PMID 34858860, 2021). "Our study describes a novel, noncanonical function of TERT and highlights the therapeutic potential of targeting noncanonical TERT functions in cancer." (PMID 33713376, 2021). "In addition, Shh signalling crosstalk with other signalling pathways during cancer development and progression, such as the Notch, Wnt and TGF‐β signalling pathways, which are also regulated by miR500A and TERT, has also been described." (PMID 33713376, 2021). "We observed positive correlation in 63% of all gene–cancer type pairs, and all genes were positively correlated with TERT across pan-cancer, suggesting that this signature is not LGG specific." (PMID 33420056, 2021). "None of the signature genes except TERT was cataloged by the expert-curated Cancer Gene Census44 (as of July 2020), although LIN9 and HELLS were recently implicated in cancer." (PMID 33420056, 2021). "Comparing telomerase activity gene signature expression to TERT_238.6 isoform percentage found significant negative correlations in 14/33 (~42%) cancer types, aligned with previous findings of TA inhibition by β-deleted TERT isoforms." (PMID 33924498, 2021). "The correlation of MYC with TERT and DKC1 in cancers suggests that oncogene activation is one of the important events that initiates cancer-specific non-telomeric functions of TERT and DKC1." (PMID 33599797, 2021). "Previous studies have reported that regulation of TERT, KRAS, and CDKN2A could serve as potential therapeutic targets in multiple cancer types." (PMID 34442467, 2021). "Correspondingly, the blockade of BRAFV600E/ERK signaling could reduce the recruitment of p-Sp1 to TERT promoter, indicating that p-Sp1 may be involved in ERK-induced GABPA binding in cancer cells." (PMID 33483600, 2021).
cancer (continued). "The results of qRT-PCRshowed that miR-195-5p in CAL-62 cells (cancer cells) was lower than in HTori-3 cells (non-cancerouscells), and the expression of TERT was higher in CAL-62 than in HTori-3 cells." (PMID 34482792, 2021). "Similarly, the application of the R-package Survminer revealed the prognostic significance of CK19 at primary diagnosis as well as of other cancer-related (CDH5 and TERT) and EMT markers (FAM83A, PTHLH, and ERBB3) at disease progression." (PMID 34834576, 2021). "TERT has long been regarded as an important marker of cancer and a target of cancer treatment, but it has not been applied to clinical treatment." (PMID 33763172, 2021). "In addition, mutations in the core promoter of the telomerase reverse transcriptase (TERT) gene create a de novo binding site for ETS2, providing a mechanism for cancer-specific telomerase reactivation." (PMID 34261460, 2021). "In this section, we will first discuss the mechanisms by which TERT is reactivated in cancer, after which we will visit the literature that focuses on the non-telomeric role of TERT in cancer." (PMID 33599797, 2021). "Instead, cancer cells are prone to maintain a highly proliferative rate; therefore, it is not surprising that TERT expression and telomerase activity (TA) represent a common feature of most of human malignancies." (PMID 33553285, 2020). "In 2000, this laboratory provided the first evidence that TERT was immunogenic and could expand cytotoxic CD8 T cells in the peripheral blood of cancer patients." (PMID 32630460, 2020). "In addition, circle-derived genomic rearrangements further contribute to the aberrant expression of cancer-relevant genes, such as doublecortin-like kinase 1 (DCLK1) and telomerase reverse transcriptase (TERT)." (PMID 32928268, 2020). "For instance, it has been shown that TERT directly interacts with β-catenin and, as a consequence, stimulates epithelial-mesenchymal transition (EMT) and stemness of cancer cells, and, by interaction with NF-κB p65, up-regulates the expression of metalloproteinases (MMPs) in cancer cells." (PMID 32560331, 2020). "TERT mRNA expression was found both in benign and malignant tumours, the frequency being higher in the latter regardless of the TERTp mutational status." (PMID 32659948, 2020). "Both TERT and TERC play important roles in tumorigenesis and could be involved in various malignant tumours through telomere maintainance." (PMID 31988393, 2020). "In these cancers with unaltered TERT promoter sequences, it is not always clear how TERT expression is activated." (PMID 32468444, 2020). "The role of epigenetic mechanisms, including DNA methylation, in regulating TERT gene expression in cancer cells is as yet not fully understood." (PMID 32468444, 2020). "In contrast, TERT expression is highly regulated, which is absent or present in low levels in somatic cells but upregulated in several types of cancer cells." (PMID 33053763, 2020). "Since the predictions made in this report are for peptides with a large coverage of MHC-II alleles in the human population, experimental validation will prove of great relevance to better understand the role of TERT CD4 T cell immunity in immune surveillance and for immunotherapy of cancer." (PMID 32630460, 2020). "Intriguingly, cancer cell lines with wild‐type (WT) TERT sequences, containing no known activating cis‐acting genetic alterations, sometimes show MAE." (PMID 33245585, 2020). "Besides, our data indicate that RT domain of TERT may act not only as an immunogen but also as a source of RNA and RNA/DNA triggering production of type I IFNs, i.e., provide in-built adjuvant(s) triggering the desired type of innate immune response against cancer cells." (PMID 32570805, 2020).
cancer (continued). "Notably, genomic clusters of viral integrations were identified in TERT (number of integration sites within a genomic cluster (NGC) of 6), KMT2B (NGC = 4)—which was recently identified to be a likely cancer driver gene—and RGS12 (NGC = 3)." (PMID 32025001, 2020). "Furthermore, the list of typically early drivers includes most other highly recurrent cancer genes, such as KRAS, TERT and CDKN2A, indicating a preferred role in early and possibly even pre-cancer evolution." (PMID 32025013, 2020). "Investigation of the specific mechanism of TERT upregulation in cancers without TPMs is equally important and worth further exploring." (PMID 33061812, 2020). "Since short telomeres are a common genomic feature of cancer cells, TPE-OLD may contribute to TERT expression/telomerase activity." (PMID 32674474, 2020). "Telomerase silencing acts as a primary barrier against cancer which is achieved by TERT transcriptional silencing or is alternatively spliced to non-telomerase coding variants." (PMID 32674474, 2020). "Unlike RNA interference therapeutics that directly suppress the expression of TERC or TERT to disrupt telomere maintenance and in cancer, hTERTC27 neither suppresses the expression levels of these genes nor restricts telomerase activity." (PMID 31035374, 2019). "This is in sharp contrast to the TG mouse models, where constitutive overexpression of TERT in the absence of genetically endowed cancer resistance by germline modification increased the cancer incidence rate." (PMID 31035374, 2019). "On the other hand, these non-canonical activities of TERT drive cancer development and/or progression by conferring cancer cells survival, proliferation, stemness, invasive phenotypes (such as epithelial-to-mesenchymal, EMT), and many other features." (PMID 31284662, 2019). "TERT is also overexpressed in the majority (>90%) of canine cancer cells regardless of their origin and there is a good correlation between TERT expression and telomerase activity in dog tissues." (PMID 31164958, 2019). "Activating genes in this branch, first of all TERT, heat shock protein 90 (HSP90AA1, HSP90AB1), importin 7 (IPO7) and p23 (PTGES3) are overexpressed in cancer, while the heat shock protein 70 (HSPA1A) and CHIP ubiquitin ligase (STUB1), both acting as suppressors, are underexpressed." (PMID 31750255, 2019). "Consistently, inhibiting the expression of GABPA or GABPB1 rather than other ETS members led to diminished TERT expression in cancer cells bearing a mutant TERT promoter." (PMID 31285550, 2019). "Telomerase reverse transcriptase (TERT) is highly expressed in more than 90% of canine cancer cells and low to absent in normal cells." (PMID 31164958, 2019). "Typically, TERT interacts with TF Sp1, binding to the vascular endothelial growth factor (VEGF) promoter and facilitating VEGF transcription/cancer angiogenesis in human cancer cells and xenograph mouse cancer models." (PMID 31284662, 2019). "TERT induction in turn further facilitates the THOR hypermethylation, promoting cancer progression." (PMID 31284662, 2019). "These proof-of-concept studies suggest the feasibility of TERT promoter methylation analyses as a useful tool in noninvasive cancer diagnosis and progression surveillance." (PMID 31284662, 2019). "A study of multiple cancers has revealed that PDAC and pancreatic acinar carcinoma do not show TERT mutations." (PMID 31608239, 2019). "Our results provide evidence of negative selection acting on the coding sequence of TERT, ultimately reaffirming its essential role in cancer." (PMID 29855388, 2018). "TERT expression is repressed in somatic cells, but not in proliferative cells in self-renewing tissues and cancers." (PMID 30073017, 2018).